SIRPB2 (signal regulatory protein beta 2)
Synonyms: PTPN1L; PTPNS1L3; dJ776F14.2
Tractability: Antibody: UniProt predicts a signal peptide or a membrane-spanning region; its Gene Ontology location is reachable by antibodies, with medium confidence.
Gene: Protein-coding gene on chromosome 20 (1,470,741 to 1,491,587, reverse strand). Ensembl gene ENSG00000196209.
Subcellular location: Membrane
Subcellular location (Human Protein Atlas): Nuclear bodies
Gene Ontology:
Cellular component: plasma membrane; membrane
Genetic constraint (gnomAD): Loss-of-function variants: 16 observed, 25.47 expected, observed/expected ratio (o/e) 0.63, 90% interval 0.42 to 0.95. The upper end of that interval is the gene's LOEUF score, 0.95, which puts it in group 4 of 6, group 1 being the genes least tolerant of losing a copy. Missense variants: 390 observed, 400.61 expected, observed/expected ratio (o/e) 0.97, 90% interval 0.89 to 1.06. Synonymous variants: 139 observed, 162.48 expected, observed/expected ratio (o/e) 0.86, 90% interval 0.74 to 0.99.
Homologues: Orthologues: chimpanzee SIRPB2 (99% identical), macaque SIRPB2 (94% identical), dog SIRPB2 (68% identical), rabbit SIRPB2 (60% identical), pig SIRPB2 (58% identical). Paralogues in human: SIRPA (23% identical), SIRPG (21% identical), SIRPB1 (21% identical), SIRPD (16% identical).